NPNT (nephronectin)
Diseases named in the same sentence as NPNT in open-access papers:
NPNT is named in the same sentence as 46 diseases in open-access papers, as found by Europe PMC text mining. Sharing a sentence is not in itself a finding about the gene and the disease. The quoted sentences say what the papers report.
breast carcinoma (6 papers, 2015 to 2025). "We recently reported that NPNT was highly expressed in primary breast cancer and associated with unfavourable prognosis." (PMID 32699247, 2020). "A study on mice with breast cancer revealed that exosomal nephronectin (NPNT) regulates the ability of breast cancer cells to colonise lung." (PMID 38200509, 2024). "Recent findings show that nephronectin is also dysregulated in breast cancer and plays a role in promoting metastasis." (PMID 33668838, 2021). "Nephronectin is overexpressed in both human and mouse breast cancer compared to normal breast tissue where the protein is absent." (PMID 33668838, 2021). "This study demonstrates a role for the extracellular matrix protein nephronectin (NPNT) in promoting experimental breast cancer brain metastasis, possibly through enhanced binding to- and migration through brain endothelial cells." (PMID 32699247, 2020). "More recently, using formalin-fixed and paraffin-embedded tissues from a well-characterised cohort of 842 Norwegian women diagnosed with invasive breast cancer (1961–2008), we showed that NPNT protein was expressed in more than 70% of all primary breast cancers." (PMID 33668838, 2021).
glomerular diseases (4 papers, 2021 to 2025). "Additionally, miR-378-3p was implicated in glomerular disease and kidney tubular fibrosis by regulating nephronectin and MAPK signaling, respectively." (PMID 34207555, 2021). "In glomerular diseases such as focal segmental glomerulosclerosis and membranous nephropathy, nephronectin is also known to be downregulated." (PMID 39946431, 2025). "Biopsies from patients with FSGS and MGN showed increased miRNA-378a-3p expression and reduced glomerular levels of NPNT suggesting miRNA-378a-3p-mediated suppression of NPNT as a novel mechanism for proteinuria in glomerular diseases." (PMID 34502062, 2021). "As TGF-β and NPNT are dysregulated in different glomerular diseases, our results of a TGF-β-mediated NPNT regulation, facilitated mainly by non-canonical pathways and post-transcriptional mechanisms, might have important impact for the development of novel therapeutic strategies in the future." (PMID 35011710, 2022).
renal agenesis (4 papers, 2020 to 2024). Renal agenesis (RA) is a form of renal tract malformation characterized by the complete absence of development of one or both kidneys (unilateral RA or bilateral RA respectively), accompanied by absent ureter(s). "Knockout of nephronectin frequently resulted in renal agenesis whereas in our study deletion of fibronectin, which likely acts on the same signaling pathway, resulted in smaller kidneys with apparently intact architecture but reduced nephrons." (PMID 38563997, 2024). "We report two Saudi Arabian consanguineous families with CAKUT phenotypes that included renal agenesis caused by missense variants in GFRA1 and NPNT, confirming the role of these two genes in human kidney development." (PMID 36292572, 2022). "Systemic deletion of nephronectin in mice (Npnt–/–) results in renal agenesis whereas conditional deletion of nephronectin in nephron progenitor cells in mice (Npntf/f; Six2-Cre) leads to mesangial sclerosis." (PMID 33553140, 2020).
COVID-19 (3 papers, 2023 to 2025). A disease caused by infection with severe acute respiratory syndrome coronavirus 2. "In conclusion, we have used genetic determinants of alternative splicing and COVID-19 outcomes obtained from large-scale studies and found compelling evidence that splicing events in OAS1, ATP11A, DPP9, NPNT, MUC1, and PMF1 have causal effects on COVID-19 severity and susceptibility." (PMID 37794074, 2023). "We identify that alternative splicing in lung, rather than total expression of OAS1, ATP11A, DPP9 and NPNT, is associated with COVID-19 severity." (PMID 37794074, 2023). "Last, we show that ATP11A, DPP9, NPNT, and MUC1 are highly expressed in lung alveolar epithelial cells, both in COVID-19 uninfected and infected samples." (PMID 37794074, 2023). "Taken together, these expression evidence suggests that the transcriptional splicing—COVID-19 outcome relationships for ATP11A, DPP9, MUC1, and NPNT were likely to be relevant in lung tissue and these signals may be especially important in alveolar epithelial cells." (PMID 37794074, 2023).
Acute hepatitis (2 papers, 2020 to 2024). Acute hepatic injury resulting from inflammation typically accompanied by increased serum alanine transaminase activity. "NPNT is an ECM protein that plays a role in acute hepatitis by promoting infiltration of CD4+ T cells or natural killer T cells through interaction with integrins." (PMID 38603681, 2024). "Importantly, a positive correlation between infiltration of CD3+ T lymphocyes and nephronectin expression was detected in human acute hepatitis biopsy specimens." (PMID 33553140, 2020).
asthma (2 papers, 2024 to 2025). "Firstly, in MR analysis between proteins and pulmonary diseases, three proteins, including EFEMP1, GM2A, and NPNT, were identified that exhibit a causal relationship with COPD while five proteins were highlighted that have causal effect on asthma." (PMID 40136421, 2025).
chronic obstructive pulmonary disease (2 papers, 2021 to 2025). A chronic and progressive lung disorder characterized by the loss of elasticity of the bronchial tree and the air sacs, destruction of the air sacs wall, thickening of the bronchial wall, and mucous accumulation in the bronchial tree. "Similarly, both proteins encoded by EFEMP1 and NPNT exhibited indirect effects on chronic obstructive pulmonary disease (COPD) by FEV1/FVC." (PMID 40136421, 2025). "Furthermore, through genome-wide association meta-analysis, NPNT was one of several genes associated with lung function and the susceptibility of developing chronic obstructive pulmonary disease (COPD)." (PMID 33668838, 2021).
diabetes (2 papers, 2021 to 2023). "Intriguingly, in a study on microdissected glomeruli from kidney autopsies of diabetes patients with nephropathy (DN) and patients without diabetes or renal disease (ND), nephronectin, a protein also related to cell‒cell adhesion, was found to be overexpressed in DN." (PMID 37626301, 2023).
kidney damage (2 papers, 2023 to 2025). "Such are these changes in nephronectin expression during and following injury that nephronectin has been identified as a marker of kidney repair following kidney damage." (PMID 39946431, 2025).
membranous glomerulonephritis (2 papers, 2022 to 2025). A slowly progressive inflammation of the glomeruli characterized by immune complex deposits at the glomerular basement membrane, resulting in a thickened membrane, and nephrotic syndrome. "In human membranous glomerulonephritis, miR-378a-3p was upregulated in urine and in glomeruli, whereas NPNT was downregulated, confirming the importance of the TGF-β–miR-378a-3p–NPNT axis in renal pathology." (PMID 35011710, 2022).
Obesity (2 papers, 2023 to 2025). Accumulation of substantial excess body fat. "Furthermore, PIK3C2G, FIBIN, CHRNA1, NPNT, MEOX1, and POU2F2 linked obesity and lung cancer, while PTPRQ, SSUH2, CILP2, CDH2, ABCA12, CPXM1, and L1CAM linked hypertension and lung cancer." (PMID 36685671, 2023).
adenoma (1 paper, 2017). A neoplasm arising from the epithelium. "NPNT (nephronectin), selectively expressed in the zona glomerulosa of human adrenal cortex and of aldosterone-producing adenomas arising from this, is shown to have roles in steroidogenesis, cell adhesion, and protection of adrenocortical cells from apoptosis." (PMID 28416583, 2017).
dementia (1 paper, 2025). Loss of intellectual abilities interfering with an individual's social and occupational functions. "In 217 clinical and neuropathologically confirmed AD versus 290 no-dementia controls donors, we identify 613 differentially expressed genes (390 up, 223 down; |log2 fold change| ≥ 0.5; BH P < 0.05), with NPNT and ADAMTS2 among the top upregulated signals." (PMID 41278792, 2025).
fibrosis (1 paper, 2022). the formation of excess fibrous connective tissue in an organ or tissue in a reparative or reactive process. "That NPNT is important in injury repair is supported by a recent analysis of BM proteomes in bleomycin-induced lung injury and fibrosis, where NPNT was one of the BM proteins that is regulated in the remodeling and resolution phases." (PMID 35552565, 2022).
Fraser syndrome (1 paper, 2023). Fraser syndrome is a rare clinical entity including as main characteristics cryptophthalmos and syndactyly. "Indeed, loss of Frem1 significantly diminished the expression of nephronectin and loss of nephronectin leads to phenotypes overlapping with Fraser syndrome phenotypes." (PMID 37047755, 2023).
Fulminant hepatitis (1 paper, 2023). Acute hepatitis complicated by acute liver failure with hepatic encephalopathy occurring less than 8 weeks after the onset of jaundice. "In a model of concanavalin A induced fulminant hepatitis, Brg1 deficiency attenuates hepatic infiltration of T lymphocytes owing to reduced production of the chemokine nephronectin." (PMID 36722664, 2023).
injury (1 paper, 2022). Damage inflicted on the body as the direct or indirect result of an external force, with or without disruption of structural continuity. "Consistent with our finding, another group employing a dynamic proteomic approach to measure fractional synthesis rates of ECM proteins demonstrated that NPNT protein was not significantly changed during the inflammatory phase of bleomycin-induced lung injury." (PMID 35552565, 2022).
Laron syndrome (1 paper, 2021). Laron syndrome is a congenital disorder characterized by marked short stature associated with normal or high serum growth hormone (GH) and low serum insulin-like growth factor-1 (IGF-I) levels which fail to rise after exogenous GH administration. "Though insulin growth factor 1 is down-regulated in Laron syndrome and induces NPNT expression, a cancer-protective role of NPNT still needs verification." (PMID 33668838, 2021). "Low levels of NPNT in Laron syndrome was correlated to low prevalence of cancer in a large epidemiological study of individuals with this syndrome." (PMID 33668838, 2021).
myocardial infarction (1 paper, 2022). Gross necrosis of the myocardium, as a result of interruption of the blood supply to the area, as in coronary thrombosis. "After a screening based on an open access RNA-seq database, we identified Nephronectin (NPNT), an extracellular protein, might be involved in cardiac repair post myocardial infarction (MI)." (PMID 35693734, 2022).
osteoporosis (1 paper, 2016). A condition of reduced bone mass, with decreased cortical thickness and a decrease in the number and size of the trabeculae of cancellous bone (but normal chemical composition), resulting in increased fracture incidence. "In summary, we have shown that NPNT is expressed by osteoblasts and its expression is reduced in osteoporosis." (PMID 27782206, 2016). "Taken together, these results demonstrate that NPNT is a paracrine angiogenic factor and may play a role in pathological osteoporosis." (PMID 27782206, 2016).
pheochromocytoma (1 paper, 2017). "NPNT was 3.6-fold upregulated in ZG, compared with ZF, when adjacent to a pheochromocytoma, but diminished or absent when adjacent to an APA." (PMID 28416583, 2017). "In addition, our own finding of NPNT as an exquisitely selective ZG protein, 3.6-fold upregulated in ZG compared with ZF when adjacent to a pheochromocytoma, but diminished or absent when adjacent to an APA, suggests the disappearance of NPNT when physiological aldosterone secretion is not required." (PMID 28416583, 2017).
pulmonary fibrosis (1 paper, 2025). Chronic progressive interstitial lung disorder characterized by the replacement of the lung tissue by connective tissue, leading to progressive dyspnea, respiratory failure, or right heart failure. "NPNT loss promoted alveolar epithelial senescence and aggravated BLM‐induced pulmonary fibrosis, whereas overexpression of NPNT in AT2 cells attenuated the development of pulmonary fibrosis." (PMID 40444575, 2025). "To determine whether the absence of NPNT expression promoted fibrogenesis, we assessed the response of NPNT knockout mice to BLM‐induced pulmonary fibrosis." (PMID 40444575, 2025). "Taken together, these data indicate that Escin, by stabilizing and restoring of NPNT protein expression, can effectively reduce fibrosis and lung pathological changes, hence highlighting its potential as a promising therapeutic target for pulmonary fibrosis." (PMID 40444575, 2025). "Utilizing these identified genes, integrated proteomic analysis of IPF patients and bleomycin (BLM)‐induced pulmonary fibrosis in mice, we discovered that NPNT and lamininα3 (LAMA3) were the only genes consistently downregulated at both mRNA and protein levels in fibrotic lung tissues." (PMID 40444575, 2025). "After screening 3105 compounds, we discovered that Escin could stabilize the protein expression of NPNT, and further alleviate pulmonary fibrosis based on this effect." (PMID 40444575, 2025). "Our findings suggest that restoring NPNT expression and its signal pathway could be a therapeutic strategy for pulmonary fibrosis." (PMID 40444575, 2025). "To investigate the potential therapeutic effects of NPNT overexpression in the alveolar epithelium on experimental pulmonary fibrosis, we generated mice with conditional overexpression of NPNT specifically in AT2 cells by crossing NPNT‐fl/fl mice with Sftpc‐Cre mice." (PMID 40444575, 2025). "Here, Nephronectin (NPNT) is identified as an antiaging molecule, a potential major regulator of the progression of pulmonary fibrosis." (PMID 40444575, 2025). "In this study, our findings showed that the protein and mRNA levels of NPNT were significantly downregulated in the lungs of IPF patients and the BLM‐induced mice pulmonary fibrosis model." (PMID 40444575, 2025). "In this study, we have established that the aberrantly downregulated NPNT in the AT2 cells promotes alveolar epithelial aging and pulmonary fibrosis." (PMID 40444575, 2025). "Therefore, we hypothesized that NPNT might act on ITGA3 to regulate the intracellular Hippo/YAP1 axis, influence the aging of alveolar epithelial cells, and subsequently impact the progression of pulmonary fibrosis." (PMID 40444575, 2025).
renal cystic dysplasia (1 paper, 2022). "The NPNT missense variant we identified was associated with severe renal cystic dysplasia but not with BRA or URA." (PMID 36292572, 2022).
cancer (9 papers, 2012 to 2025). A tumor composed of atypical neoplastic, often pleomorphic cells that invade other tissues. "For instance, C2 expresses TIMP3, a metalloproteinase inhibitor that aids in the ECM remodeling, and NPNT, a gene reported to be related to development and cancer processes." (PMID 40111904, 2025). "For instance, C2 expresses TIMP3, a metalloproteinase inhibitor that aids in the extracellular matrix remodeling, and NPNT, a gene reported to be related to development and cancer processes." (PMID 39005414, 2024). "During the last two decades it has become evident that nephronectin also plays a role during cancer progression and in particular metastasis." (PMID 33668838, 2021). "Cancer cells expressing elevated levels of nephronectin acquire increased ability to colonise distant organs." (PMID 33668838, 2021). "In this review, we summarise the literature on nephronectin, analyse the structure and domain-related functions of nephronectin and link these functions to potential roles in cancer progression." (PMID 33668838, 2021). "NPNT also induced hormone production (aldosterone) in a type of adenoma, indicating that NPNT has diverse functional roles also in cancer." (PMID 33668838, 2021). "As NPNT seems to play a pivotal role in organogenesis and differentiation, it is not surprising that the protein can be exploited also during cancer progression." (PMID 33668838, 2021). "To understand the role of NPNT in cancer progression, we will start by reviewing the structure and domain-related functions of NPNT." (PMID 33668838, 2021). "Other proteins are known inducers of epithelial to mesenchymal transition (EMT) (i.e. Laminins) or cancer cell spreading (i.e., CCN2, NPNT, WASF2, SERPINE, MAP4K4)." (PMID 40410902, 2025).
tumor (5 papers, 2017 to 2025). "The expression of NPNT was significantly downregulated in tumours, which led to the attenuation of NPNT-associated signalling pathways upon the reduction of NPNT expression." (PMID 40429821, 2025). "NPNT was upregulated 3.63 fold (p = 2.58E−12) in tumour tissue compared to normal breast tissue, indicating a dysregulation of NPNT gene expression in BC." (PMID 32699247, 2020). "After a microarray comparing tumor subtypes, in which NPNT (nephronectin) was the most highly (>12-fold) upregulated gene in ZG-like APAs, we aimed to determine its role in physiological and pathological aldosterone production." (PMID 28416583, 2017). "As described, FGFBP1, STC1, and NPNT proteins have tumor‐promoting effect thus, downregulation of these proteins could have contributed to the synergistic effect in our study." (PMID 38217262, 2024). "Nephronectin (NPNT) has also been shown to be a key regulator of tumor metastasis." (PMID 36353536, 2022). "NPNT was expressed in all tumours, with highest expression in the BT474 tumours." (PMID 32699247, 2020).
infection (2 papers, 2023). The state of being infected such as from the introduction of a foreign agent such as serum, vaccine, antigenic substance or organism. "Alternative splicing of NPNT had a high posterior probability for critical illness (1.00), and hospitalization (1.00), but had a low posterior probability for reported infection (0.02)." (PMID 37794074, 2023).
respiratory system diseases (1 paper, 2024). "Lamin A/C (LMNA, P02545) is correlated with white blood cell count, and Nephronectin (NPNT, Q6UXI9) has been identified as a major gene influencing lung function, respiratory system diseases, chronic obstructive pulmonary disease, and peak expiratory flow rate." (PMID 39192889, 2024).
NPNT also shares sentences with these, for which no sentence is quoted: silicosis (3 papers); pancreatic cancer (2); Arthritis (1); atherosclerosis (1); breast disease (1); chronic hepatitis (1); focal segmental glomerulosclerosis (1); heart failure (1); Hepatitis (1); hepatoblastoma (1); Hypertension (1); idiopathic pulmonary fibrosis (1); liver disease (1); lung carcinoma (1); nephropathy (1); preeclampsia (1); pulmonary diseases (1); type 1 diabetes mellitus (1); viral pneumonia (1).